HIF1A (hypoxia inducible factor 1 subunit alpha)
Diseases named in the same sentence as HIF1A in open-access papers (continued):
Sharing a sentence is not in itself a finding about the gene and the disease.
rheumatoid arthritis (continued). "Interestingly, in the context of RA, cytoplasmic and nuclear overexpression of HIF-1α is described in the synovial lining in rheumatoid arthritis patients offering another potential target for antiarthritic activity of 2ME2." (PMID 19409094, 2009). "Although the protective effects of HIF-1α in osteoarthritis and rheumatoid arthritis in mice have been documented, there is no any clear data in this field showing the differential expression of HIF-1α in the normal people and patients with osteoarthritis." (PMID 32587244, 2020). "“MANALO_HYPOXIA_UP” (genes up-regulated in response to both hypoxia and overexpression of an active form of HIF1A), another candidate biological gene sets associated with SIS, played a vital role in the pathogenesis of osteoarthritis (OA) and rheumatoid arthritis (RA)." (PMID 32690583, 2020). "A number of published articles reported that HIF1α is a key regulator in inflammation and autoimmune diseases, such as systemic lupus erythematosus (SLE), rheumatoid arthritis (RA), type 1 diabetes (T1DM), multiple sclerosis (MS), psoriasis, and inflammatory bowel disease (IBD)." (PMID 30795546, 2019). "In an in vivo model of rheumatoid arthritis, transforming growth factor beta (TGF-β) induction also resulted in accumulating succinate levels, which were found to activate the NLRP3 inflammasome in a HIF1A-dependent manner." (PMID 30809153, 2019). "In rheumatoid arthritis (RA), the CD27 IgD naïve B cell subset produces IL-6, and both HIF-1α and IL-6 are co-expressed in RA patient B cells." (PMID 40791591, 2025). "Notably, the expression level of IL-38 is abnormal in rheumatoid arthritis (RA) patients, and IL-38 can restrain inflammatory responses in collagen-induced arthritis (CIA) mice via Sirtuin1/Hypoxia-inducible factor-1α (SIRT1/HIF-1α) signaling pathway." (PMID 34539413, 2021). "Andrographolide reduces MMP-1, MMP-3, and MMP-9 expression of rheumatoid arthritis fibroblast-like synoviocytes (RA-FLS) in hypoxia, decreasing HIF-1α expression and interfering with HIF-1α binding to DNA." (PMID 33374961, 2020). "However, none of the compounds targeting HIF-1α has been assessed in clinical trials for rheumatoid arthritis." (PMID 32226427, 2020). "Hypoxia promoted cellular proliferation of rheumatoid arthritis synovial fibroblasts (RASFs), and induced cell migration and angiogenic tube formation of human dermal microvascular endothelial cells (HDMECs), which were accompanied with the increased expression of G6PI and HIF-1α." (PMID 28067317, 2017). "In Rheumatoid arthritis (RA) patients have shown negative correlations between expression of HIF-1α in Treg and disease activity score 28 (DAS28)." (PMID 40963621, 2025). "To date, overexpression of HIF-1α was detected in the serum, skin tissue, and urine of different inflammatory autoimmune diseases, such as systemic lupus erythematosus (SLE), rheumatoid arthritis (RA), systemic sclerosis (SSc), and psoriasis." (PMID 36761171, 2022). "HIF-1α acts as a key regulator during inflammation, increasing pro-inflammatory cytokines (e.g., TNF-α, IL-1β, IL-6, and IL-8), matrix metalloproteinases (e.g., MMP-1, MMP-3, and MMP-9), and pathways of glucose metabolism in rheumatoid arthritis (RA)." (PMID 33374961, 2020). "In the synovium of rheumatoid arthritis (RA) rats, hypoxic TGF-β1 induction increased succinate accumulation due to the reversal of succinate dehydrogenase (SDH) activation and induced NLRP3 inflammasome activation in a manner dependent on HIF-1α induction." (PMID 28003810, 2016). "In autoimmune diseases such as rheumatoid arthritis (RA), systemic lupus erythematosus (SLE), multiple sclerosis (MS), and membranous nephropathy (MN), dysregulation of this axis is characterized by excessive HIF-1α signaling and relative insufficiency of the IDO1/AhR pathway." (PMID 41869303, 2026).
myocardial ischemia (78 papers, 2010 to 2025). A disorder of cardiac function caused by insufficient blood flow to the muscle tissue of the heart. "Together, these studies provide novel evidence that mice with myeloid-specific Hif1a deletion experience increased susceptibility to myocardial ischemia and reperfusion injury, essentially resembling the findings in mice with induced global deletion of Hif1A." (PMID 36247475, 2022). "While the current studies directly implicate HIF1A in attenuating myocardial ischemia and reperfusion injury, other studies have also implicated HIF2A in cardioprotection." (PMID 36247475, 2022). "Increased expression of HIF-1α levels is associated with early response to myocardial ischemia or infarction, and the risk of arterial hypertension." (PMID 31594995, 2019). "This was associated with increased myocardial expression in HIF-1α in the animals fed with high fat diet, indicating local myocardial ischemia." (PMID 26840416, 2016). "Cardiac ischemia caused by hypoxia secondary to AQP1 deficiency stabilized the expression of HIF-1α in endothelial cells and subsequently decreased microvascular permeability, resulting in the development of edema." (PMID 26348407, 2015). "Additionally, treating rats with myocardial ischemia using recombinant adeno-associated virus expressing HIF-1α improves cardiac function and enhances cardiac capillary density." (PMID 38539163, 2024). "Previous research has shown that cardiac ischemia can promote angiogenesis by activating the HIF-1α/VEGF pathway." (PMID 41295364, 2025). "HIF-1α plays a critical role in adaptive responses to myocardial ischemia by promoting formation of collateral arteries and inhibit cardiomyocyte death." (PMID 40729334, 2025). "Further research is needed to confirm the role of P2X7Rs in hypoxic cardiomyocytes via HIF-1α/VEGF in experimental animal models of cardiac ischemia, such as the LAD artery ligation model." (PMID 41295364, 2025). "Our data revealed that the administration of roxadustat after myocardial ischemia can increase the expression of HIF-1α and upregulate HIF-1α-related target genes, which was associated with the attenuation of adverse remodeling." (PMID 38994928, 2024). "One possible explanation is that increased expression of HIF-1α during myocardial ischemia serves as an adaptive response to promote angiogenesis, and then favor mitochondrial respiration and facilitate aerobic glucose metabolism." (PMID 39605071, 2024). "Recent studies suggest that HIF-1α in neutrophils mitigates myocardial injury during acute myocardial ischemia and reperfusion by inducing the expression of the neuronal guidance protein netrin-1." (PMID 37233182, 2023). "HIF-1α is involved in pathophysiological processes such as cerebrovascular disease, neurological injury, and myocardial ischemia." (PMID 36541246, 2023). "In summary, this study demonstrates that DNA hypermethylation of the Bmp4 promoter in cardiomyocytes caused by prenatal DEX exposure substantially dampens promoter binding of transcription factor HIF-1α induced by cardiac ischemia and hypoxia." (PMID 36746787, 2023). "In summary, HIF-1α critically influences various aspects of neutrophil function, which is pivotal in the context of myocardial ischemia and reperfusion." (PMID 37233182, 2023). "In contrast to the extensively researched HIF-1α, which has been the focus of numerous myocardial ischemia studies, investigations into HIF-2α’s role in myocardial ischemia are comparatively limited." (PMID 37233182, 2023). "Further research is needed to fully understand the mechanisms involved in HIF-1α’s nuanced regulation of neutrophil function and its effects on the inflammatory response after myocardial ischemia." (PMID 37233182, 2023). "Current studies have found that HIF-1α is involved in pathophysiological processes such as cerebrovascular disease, neurological injury, tumors, myocardial ischemia, pulmonary hypertension, preeclampsia, and fetal growth retardation in utero." (PMID 36541246, 2023).
myocardial ischemia (continued). "HIF-1α can protect myocardial ischemia–reperfusion injury by improving mitochondrial function, decreasing cellular oxidative stress, activating related genes, and interacting with noncoding RNAs." (PMID 37238718, 2023). "Intriguingly, recent evidence emphasizes the significance of HIF-1α’s function in neutrophils during myocardial ischemia and reperfusion injury." (PMID 37233182, 2023). "Together, these studies highlight a functional role of myeloid-dependent HIF1A in attenuating myocardial ischemia and reperfusion, and its transcriptional target netrin-1." (PMID 36247475, 2022). "This highlights that HIF1A coordinates the transcriptional response in response to myocardial ischemia." (PMID 36247475, 2022). "Taken together, these studies provide additional support for the concept that myeloid HIF1A provides cardioprotection through transcriptional induction of its target gene netrin-1, leading to attenuated myocardial ischemia and reperfusion injury." (PMID 36247475, 2022). "Autophagy induced by HIF-1α/BNIP3 signaling pathway plays a protective role in myocardial ischemia-reperfusion injury." (PMID 36187470, 2022). "Of note, allopurinol is reported to stabilize cardiac HIF-1α and heme oxygenase 1 protein expression, conferring synergistic cardioprotection against myocardial ischemia/reperfusion injury in diabetic rats." (PMID 36297636, 2022). "The increase of HIF-1α expression is an adaptive response of the body to myocardial ischemia and hypoxia." (PMID 38680230, 2022). "Together, these results indicate that PMN-dependent Hif1a deficiency is associated with elevated myocardial ischemia and reperfusion injury and implicates PMN-dependent HIF1A in cardioprotection." (PMID 36247475, 2022). "HIF1A is ubiquitously expressed, including cells involved in myocardial ischemia and reperfusion injury, such as cardiomyocytes, vascular endothelial cells, and myeloid cells." (PMID 36247475, 2022). "The objective of this study is to investigate the protective mechanism of dexmedetomidine (Dex) in myocardial ischemia/reperfusion (MIR)-induced acute lung injury (ALI) of diabetic rats by inhibiting hypoxia-inducible factor-1α (HIF-1α)." (PMID 35605218, 2022). "Mice with heterozygous defects of HIF-1α have a reduced protective effect of hypoxic preconditioning in a model of cardiac ischemia and a dramatic effect on carotid body neural activity and ventilatory adaptation to chronic hypoxia." (PMID 34422800, 2021). "There is evidence that Panax Notoginseng saponins can individually regulate apoptosis and mitochondrial autophagy by the PI3K/Akt and HIF-1α/BNIP3 pathways to protect rat heart from myocardial ischemia and its reperfusion injury." (PMID 34012683, 2021). "Accumulation of HIF‐1α induced by DMOG seems to protect tissue against myocardial ischemia injury within 3 hr and then to induce angiogenesis in ischemic skeletal muscles of mice after several days or in human critical limb ischemia over 2 weeks." (PMID 33356010, 2021). "HIF-1α/BNIP3 signaling pathway-induced-autophagy plays protective role during myocardial ischemia-reperfusion injury." (PMID 33013381, 2020). "The aim of this study was to identify the role of miR-155 in the myocardial ischemia/reperfusion (I/R) injury through targeting hypoxia-inducible factor 1-alpha (HIF-1α)." (PMID 31807249, 2019). "HIF-1α is an important regulator in myocardial ischemia reperfusion injury in healthy hearts and can augment the purine signaling to facilitate myocardial protection." (PMID 30510628, 2018). "MIF was shown to be cardioprotective in experimental myocardial ischemia/reperfusion injury and its expression is regulated by the transcription factor hypoxia-inducible factor (HIF)-1α." (PMID 29027966, 2017).
myocardial ischemia (continued). "Previous studies from our group have demonstrated that sevoflurane post-conditioning (SPC) protects against myocardial ischemia reperfusion injury via elevating the intranuclear expression of hypoxia inducible factor-1 alpha (HIF-1α)." (PMID 28659817, 2017). "HIF-1α upregulation occurs in certain organs after exposure to hypoxia and is an early response to myocardial ischemia in humans, leading to angiogenesis and improving myocardial cell survival." (PMID 29170412, 2017). "Linking the AKT/GSK-3β pathway and HIF-1α in myocardial ischemia/reperfusion injury advances our understanding of the molecular mechanisms underlying the cardioprotection of asiatic acid." (PMID 27657024, 2016). "Increases in the HIF-1α levels of vascular endothelial cells represent one of the earliest responses to myocardial ischemia and infarction." (PMID 26348407, 2015). "Hypoxia inducible factor-1 alpha (HIF-1α) is a transcription factor mediating early and late responses to myocardial ischemia." (PMID 24498007, 2014). "HIF-1α itself is a transcription factor mediating early as well as late responses to myocardial ischemia." (PMID 24498007, 2014). "In particularly, HIF-1α activation plays an essential role in triggering cellular protection and metabolic alterations in response to oxygen deprivation during myocardial ischemia." (PMID 25238237, 2014). "This also relates to a possible role of hypoxia-inducible factor-1α (HIF-1α) as a regulator of SgII production after myocardial ischemia." (PMID 22655045, 2012). "It has been demonstrated that up-regulation of HIF-1α in cardiomyocytes is protective against myocardial ischemia in vivo." (PMID 22506063, 2012). "HIF-1α levels reportedly accumulate during cardiac ischemia." (PMID 41295364, 2025). "Chronic hypoxia-induced Hif1a enhances myocardial ischemia tolerance by promoting mitophagy." (PMID 40491449, 2025). "Besides, key genes that mark cardiac ischemia/hypoxia, such as HIF1α and other related genes, were also elevated." (PMID 39377453, 2025). "HIF-1α can upregulate iNOS levels, thereby attenuating myocardial ischemia–reperfusion injury." (PMID 38539163, 2024). "However, the regulatory mechanisms for Hif1α and aerobic glycolysis during the reperfusion following myocardial ischemia is incompletely understood." (PMID 38421727, 2024). "Furthermore, the HIF-1α/BNIP3-mediated regulation of mitophagy that we have discovered provides new insights into potential therapeutic targets for myocardial ischemia–reperfusion injury." (PMID 38539069, 2024). "Contrarily, another study investigating IPoC in myocardial ischemia showed that microRNA-214 may participate in the protective function of IPoC by down-regulating HIF1α." (PMID 36908508, 2023). "In the present study, we further observed that DNA hypermethylation of bone morphogenetic protein 4 (Bmp4) promoter in cardiomyocytes caused by prenatal DEX exposure substantially dampened the binding activity of transcription factor HIF-1α induced by cardiac ischemia." (PMID 36746787, 2023). "Therefore, the HIF-1α/BNIP3 signaling pathway can protect the myocardial ischemia-reperfusion injury by inducing autophagy." (PMID 35586047, 2022). "Together, these studies highlight that the HIF1A pathway could be utilized as a therapeutic target for myocardial ischemia and reperfusion injury." (PMID 36247475, 2022). "For example, it is possible that patients experiencing myocardial ischemia and reperfusion injury could be treated with recombinant netrin-1 to activate the HIF1A-netrin-1 pathway for cardioprotection." (PMID 36247475, 2022). "In support of the thrombotic hypothesis, myocardial ischemia was evident by the increased nuclear accumulation of HIF1α protein and induction of Vegfa expression." (PMID 34793333, 2022).
myocardial ischemia (continued). "TMSB4-transfected BMMSCs might significantly improve recovery from myocardial ischemia and promote the generation of HIF-1α and p-HIF-1α via the AKT pathway, and inhibit the degradation of HIF-1α via the PHD and FIH pathways." (PMID 34178995, 2021). "Similarly, a previous study reported a sex-related dimorphic response of HIF-1α expression in myocardial ischemia, where increased HIF-1α expression in hearts from females both under normoxic and, more strikingly, under hypoxic conditions." (PMID 31942001, 2020). "During myocardial ischemia, the enhanced iNOS expression could be a consequence of activation of Hypoxia-inducible factor 1α (HIF-1α) signaling." (PMID 30510628, 2018). "Using cardiac ischemia and brain hypoxia models as a guide to the broader framework of phenotypic plasticity, HACT is enabled by a metabolic shift induced by HIF-1α and there are less injuries caused by Ca+2 overload, via channel or complex-protein remodeling, or decreased channel abundance." (PMID 28804462, 2017). "Similar to the hypoxic tumor microenvironment, myocardial ischemia is characterized by hypoxia, and the consequent activation of HIF-1α plays a critical role in triggering cellular mechanisms of protection against the consequences of oxygen deprivation in the myocardium." (PMID 29170412, 2017). "Additionally, single-target anti-HIF-1α therapeutics has demonstrated life-threatening problems with physiological responses to other diseases such as cardiac ischemia, renal disease and irritable bowel syndrome." (PMID 26536104, 2015). "Thus, cardiac upregulation of HIF-1α occurs during IPC, and partial deficiency or silencing of HIF-1α causes complete loss of IPC-induced protection against myocardial ischemia." (PMID 26042040, 2015). "HIF-1α is one of the earliest responses to myocardial ischemia and infarction." (PMID 26348407, 2015). "Moreover, co-immunoprecipitation studies confirmed a co-localization of both Per2 and Hif1α in the nucleus during myocardial ischemia." (PMID 23977055, 2013). "The current study showed that the increase in HIF-1α and VEGF in hypoxic cardiomyocytes was associated with increased P2X7R expression, suggesting that P2X7R can induce pro-angiogenic signaling in the early stage of cardiac ischemia by activating the HIF-1α/VEGF pathway." (PMID 41295364, 2025). "Research has confirmed that hydroxysafflor yellow A (HSYA) can inhibit myocardial cell ferroptosis by activating HIF-1α, which ultimately increases the expression of SLC7A11 and GPX4, thereby reducing myocardial ischemia/reperfusion injury in mice." (PMID 40691131, 2025). "Gene-metabolite interaction network analysis revealed the significant roles of key regulatory molecules such as HIF1A, adenosine, TBK1, ATP, NRAS, and EIF2AK3, in the pathogenesis of myocardial ischemia." (PMID 38818463, 2024). "Danshensu improved coronary flow, heart rate, and left ventricular developed pressure in isolated rat hearts myocardial ischemia model, while Danshen increased HIF1α and VEGFA expression, improving cardiac function and angiogenesis in myocardial ischemia mice." (PMID 39273041, 2024). "Additionally, HIF-1α may serve as an early molecular marker for myocardial ischemia or infarction." (PMID 40376262, 2024). "Our transcriptional data provide evidence that significantly higher levels of hypoxia-related and proangiogenic genes (HIF1a, VEGFA, FGF2, eNOS, SOX17, and LRG1) promote neovascularization at the site of increased cardiac ischemia." (PMID 36371548, 2023). "During myocardial ischemia and reperfusion, both of HIF-α subunits, HIF-1α and HIF-2α, are stabilized." (PMID 37233182, 2023). "In summary, HIF-1α and HIF-2α, while both involved in cellular responses to hypoxia during myocardial ischemia and reperfusion, exhibit differences in expression patterns, sensitivities to oxygen partial pressure, and target gene regulation." (PMID 37233182, 2023).